CXCR4 (C-X-C motif chemokine receptor 4)
Diseases named in the same sentence as CXCR4 in open-access papers (continued):
Sharing a sentence is not in itself a finding about the gene and the disease.
gastric cancer (continued). "In addition, a meta-analysis reported that Cxcr4 expression in primary human gastric cancer tissues was positively associated with tumor progression and disease prognosis, including vascular invasion." (PMID 29340033, 2017). "Moreover, we found that both cytoplasmic and nuclear CXCR4 are strongly expressed in primary gastric cancer and the cytoplasmic pattern of CXCR4 tends to be associated with a shorter overall survival than nuclear staining." (PMID 24659999, 2014). "Lauren classification (P=0.025), T classification (P=0.002), N classification (P=0.001), distant metastasis (P<0.001), TNM stage (P<0.001), and CXCR4 expression (P<0.001) were statistically significant risk factors affecting overall survival of patients with gastric cancer." (PMID 23936528, 2013). "In addition, we previously reported that Cxcl12/Cxcr4 signaling is involved in activation and recruitment of cancer-associated fibroblasts during gastric carcinogenesis, and that aberrant expression of Cxcl12 accelerates gastric cancer development." (PMID 29340033, 2017). "The CXCL12/CXCR4 axis is highly relevant to human gastric cancer, where it promotes invasion, metastasis, and therapeutic resistance." (PMID 40673273, 2025). "It has been demonstrated that the RUNX2 transcription factor upregulates the expression of the chemokine receptor CXCR4, promoting the metastatic ability of human gastric cancer." (PMID 38474372, 2024). "Retraction: Jun Xiao, Hao Lai, Sheng-Hong Wei, Zai-Sheng Ye, Fu-Sheng Gong, Lu-Chuan Chen (2019), lncRNA HOTAIR promotes gastric cancer proliferation and metastasis via targeting miR-126 to active CXCR4 and RhoA signaling pathway." (PMID 38695659, 2024). "In conclusion, the present study identified two subtypes and a prognostic signature for stage I and stage II gastric cancer based on NRGs, such as CXCR4 and NFE2L2." (PMID 38221932, 2024). "Results indicated that CXCR4 and NFE2L2 were the independent risk factor for the prognosis of gastric cancer (p < 0.05)." (PMID 38221932, 2024). "The differences in the expression of hub genes, PTGS2, MMP9, MMP2, and CXCR4 genes were higher than normal gastric tissues in gastric cancer, and PPARG gene was lower than normal gastric tissues." (PMID 38457601, 2024). "For instance, the relationship between PGK1 and CXCR4/CXCL12/β-catenin has been established in gastric cancer and hepatocellular carcinoma." (PMID 38163864, 2024). "CXCR4 has also been identified as a significant unfavorable prognostic marker in renal and stomach cancers among the 17 major human cancer types based on the TCGA data." (PMID 37749552, 2023). "Both an invasive gastric cancer cell culture and gastric cancer tissues displayed significant levels of CXCR4 expression." (PMID 38049463, 2023). "Since PGK1 is described to influence CXCR4 and β-catenin expression in gastric cancer cells, promoting peritoneal carcinomatosis, KATO III cells were incubated with 100 μM TatA for 24 h, and CXCR4 and β-catenin expression was evaluated by RT-qPCR." (PMID 37767160, 2023). "This study aims to reveal the molecular mechanism of the cancer stem cells (CSCs) marker gene CXCR4 in gastric cancer (GC) growth and metastasis through scRNA-seq combined with bulk RNA-seq." (PMID 37679408, 2023). "Meanwhile, disrupting CXCL12/CXCR4-mediated signaling pathways also contributes to inhibiting further metastasis of gastric cancer at a later stage." (PMID 37047625, 2023). "Then, we chose three genes (CXCR4, TNFSF18, and TAP1) that were all linked to the length of survival for patients with stomach cancer." (PMID 35509844, 2022). "SRC plays an important role in the migration of gastric cancer cells by mediating a potential CXCR4-EGFR crosstalk and sequentially activating the EGFR-Akt/ERK axis." (PMID 36299773, 2022). "The results of the presented research suggest a significant role of VEGF and CXCR4 in the biology of gastric cancer." (PMID 35877436, 2022).
gastric cancer (continued). "Curcumol treats chronic atrophic gastritis and gastric cancer by decreasing SDF-1α/CXCR4/VEGF expression." (PMID 36131788, 2022). "According to the authors, CXCR4 expression predicts lymph-node status, including micrometastasis in gastric cancer." (PMID 35877436, 2022). "KDM6B was found to promote the proliferation and metastasis of gastric cancer cells in vitro and in vivo via CXCR4." (PMID 36564369, 2022). "Further testing showed that the SDF-1α, CXCR4, NF-κB, and p-NF-κB protein expressions in gastric cancer cells were declined after a treatment with curcumol and the positive drug Fuzheng Huowei decoction." (PMID 36159583, 2022). "To date, only a few reports have revealed the relationship between LNMM and CXCR4 expression in gastric cancer." (PMID 35877436, 2022). "Through the research on this subject, it is proved that curcumol can treat CAG and reverse the progression of gastric cancer by regulating the SDF-1/CXCR4 axis." (PMID 36159583, 2022). "We also analyzed the IHC Score of KDM6B and CXCR4 in gastric cancer tissues and found that they were positively correlated, too." (PMID 36564369, 2022). "There are some controversies about the relationships between CXCR4 expression, Lauren classification, and the differentiation of gastric cancer." (PMID 35877436, 2022). "In this paper, we confirmed that curcumol exerts anti-inflammatory activity by regulating the SDF-1/CXCR4 axis and suppressing the NF-κB pathway during the development of gastric cancer." (PMID 36159583, 2022). "In order to prove that curcumol exerts its regulatory function by regulating the SDF-1α/CXCR4/NF-κB axis, this study cotreated gastric cancer cells with SDF-1α overexpressing lentivirus and curcumol." (PMID 36159583, 2022). "Previous studies have shown that gastric cancer patients with high expression of CXCR4 have a poor prognosis and therefore, CXCR4 can be used as a prognostic marker of gastric cancer." (PMID 36564369, 2022). "H. pylori also promotes the release of TNF-α from macrophages and thus up-regulates the expression of C-X-C motif chemokine receptor 4 (CXCR4) in gastric cancer cells." (PMID 35795038, 2022). "Previous studies have shown that CXCR4 plays an important role in the development of many tumors, including gastric cancer, and thus, we next focused on CXCR4." (PMID 36564369, 2022). "When SDF-1α was overexpressed, the protein expressions of SDF-1α, CXCR4, and NF-κB were all increased, which would offset the inhibition from curcumol on gastric cancer cells." (PMID 36159583, 2022). "In this study, we found that Curcumol significantly reduces the SDF-1α/CXCR4/VEGF protein levels in gastric cancer cells." (PMID 36131788, 2022). "In conclusion, curcumol effectively protects gastric tissue and inhibits the viability of gastric cancer cells, and curcumol regulates SDF-1α/CXCR4/NF-κB to play a therapeutic role in chronic atrophic gastritis and gastric cancer." (PMID 36159583, 2022). "Curcumol regulates SDF-1α/CXCR4/NF-κB to play a therapeutic role in chronic atrophic gastritis and gastric cancer." (PMID 36159583, 2022). "Our results regarding the prognostic role of VEGF and CXCR4 expression in gastric cancer must be interpreted with caution due to the small sample size." (PMID 35877436, 2022). "We analyzed the mRNA expression levels of KDM6B and CXCR4 in GEPIA’s gastric cancer database and found that they were positively correlated." (PMID 36564369, 2022). "After adding the lentivirus overexpressing SDF-1α to the curcumol treatment group, it was found that SDF-1α, CXCR4, NF-κB, and p-NF-κB protein expressions were all increased, and the effect of curcumol on gastric cancer cells was reversed." (PMID 36159583, 2022). "Further studies showed that the knockdown or addition of the KDM6B enzyme activity inhibitor, GSK-J4, can downregulate the expression of CXCR4 in gastric cancer cells." (PMID 36564369, 2022).
gastric cancer (continued). "In gastric cancer, several studies were able to show the upregulation of CXCR4 in cancer tissue either by IHC or RT-PCR compared to normal gastric tissues." (PMID 35877436, 2022). "Positivity rates for CXCR4 at the primary gastric cancer lesions reach 32.3–80.0% by IHC detection, which are significantly higher than those in the adjacent normal mucosa tissues." (PMID 35877436, 2022). "In this study, we proved that Curcumol has therapeutic effects on CAG and that it reverses gastric cancer progression by manipulating the angiogenic activity mediated by the SDF-1/CXCR4 axis." (PMID 36131788, 2022). "Previous studies demonstrated that the CXCL12/CXCR4 axis plays an important role in the metastasis of many malignancies, including gastric cancer." (PMID 35877436, 2022). "The aim of this study was to investigate the expression and prognostic significance of VEGF and CXCR4, which are responsible for angiogenesis and progression in gastric cancer." (PMID 35877436, 2022). "Although VEGF and CXCR4 have been characterized individually, little is known about the co-expression of these factors in human gastric cancer." (PMID 35877436, 2022). "Curcumol functions as a therapeutic factor in chronic atrophic gastritis and gastric cancer by downregulating SDF-1α/CXCR4/VEGF expression." (PMID 36131788, 2022). "In vitro functional studies have shown that CXCR4 promotes the proliferation, migration and invasion of gastric cancer cells and can be used as an independent prognostic indicator for GC patients." (PMID 35388021, 2022). "Univariate analysis and multivariate analysis indicated that CXCR4 was an independent prognostic indicator for TCGA gastric cancer patients." (PMID 34322132, 2021). "In gastric cancer, low levels of miR-204-5p are correlated with lymph node metastasis, and this miRNA negatively regulates C-X-C motif chemokine receptor 4 (CXCR4), which can provoke metastasis by blocking anoikis." (PMID 33435156, 2021). "Because CXCR7 and CXCR4 are co-expressed in gastric cancer cells and can form homodimers and heterodimers." (PMID 34858476, 2021). "We have previously shown that miR-200c targets VEGFR and MMP9 in gastric cancer cell lines and miR-200c inhibits CXCR4 indirectly by targeting ZEB1." (PMID 33673143, 2021). "In vitro functional studies had shown that CXCR4 promoted the proliferation, migration, and invasion of gastric cancer cells." (PMID 34322132, 2021). "Our results indicate that CXCR4 can be used as a prognostic indicator for patients with gastric cancer." (PMID 34759953, 2021). "Many studies have found that SDF-1/CXCR4 axis regulates gastric cancer proliferation, migration, invasion, metastasis and angiogenesis." (PMID 34858476, 2021). "CXCR4 promotes the phosphorylation of c‐Met and then induces epithelial‐to‐mesenchymal transition and accelerates migration in gastric cancer cells." (PMID 34555268, 2021). "EBV is capable of manipulating C-X-C motif chemokine receptor 4 (CXCR4) expression to maintain latency in EBV-related gastric carcinoma." (PMID 34572593, 2021). "We found that gastric cancer patients with overexpression of CXCR4 had lower TMB, purity, higher CYT, and CD8 T‐cell infiltration." (PMID 32306562, 2020). "The CXCR4/mTOR signaling pathway is also thought to play a role in promoting migration and inducing autophagic cell death in the peritoneal diffusion of gastric cancer cells." (PMID 32477008, 2020). "CAFs are also reported to promote invasion through the CXCR4 pathway in gastric cancer and a CXCR4 antagonist blocked the invasiveness of gastric cancer." (PMID 32731484, 2020). "We found that DCLK1 expression significantly correlates with both TGFB1 and CXCL12 and their receptors TGFBR1, TGFBR2, and TGFBR3, and CXCR4, respectively, in colon and stomach cancer patients." (PMID 31979136, 2020).
gastric cancer (continued). "The activation of CXCR4 under conditions of hypoxic stress is consistent with the findings of previous studies that hypoxic stimuli induces CXCR4 in osteosarcoma, synoviocyte and gastric cancer." (PMID 30760238, 2019). "Some studies have shown CXCR4 pathway can promote epithelial-mesenchymal transition in gastric cancer cells." (PMID 30808413, 2019). "It has been reported that CXCR4 was involved in mTOR-dependent migration of gastric carcinoma cells." (PMID 31882811, 2019). "High expression levels of EGFR and CXCR4 mRNA and protein were observed among primary tumours and human gastric cancer cell lines, with an upraised possibility to evoke peritoneal carcinomatosis." (PMID 29867026, 2018). "Our findings demonstrated that regorafenib effectively inhibited cell proliferation and invasion of gastric cancer cells via decreasing the expression of CXCR4 and further reducing the transcriptional activity of Wnt/β-Catenin pathway." (PMID 28489887, 2017). "It has been reported that Wnt/β-catenin pathway played critical roles in the development and progression in gastric cancer, and CXCR4 has been published as an upstream regulator of Wnt/β-catenin pathway." (PMID 28489887, 2017). "We have showed that regorafenib inhibited gastric cancer cells growth and invasion via downregulating the expression of CXCR4." (PMID 28489887, 2017). "Our findings demonstrated that regorafenib inhibited gastric cancer cells proliferation and invasion via decreasing the expression of CXCR4 and further reducing the transcriptional activity of Wnt/β-Catenin pathway." (PMID 28489887, 2017). "Chemokines and chemokine receptor 4 (CXCR4) plays an important role in gastric cancer growth, invasion and metastasis." (PMID 28489887, 2017). "The results indicated that regorafenib decreased the expression of CXCR4 in a dose–dependent and a time–dependent manner in gastric cancer cells." (PMID 28489887, 2017). "We demonstrate that DC-SIGNR facilitates gastric cancer liver metastasis mediated by HNRNPKP2 regulated by STAT5A via the CXCL12/CXCR4 biological axis." (PMID 28403883, 2017). "MIST1 expression in human gastric antrum was recently described, and epithelial Cxcr4 expression in human gastric cancer tissue has been also reported." (PMID 29340033, 2017). "CXCR4 has been reported to be overexpressed in more than 20 different tumors, including gastric cancer." (PMID 28489887, 2017). "Our data suggested that the potential underlying mechanism of the inhibition effect of regorafenib in gastric cancer cells was correlated with CXCR4." (PMID 28489887, 2017). "In our study, we found that the anti-tumor effects of regorafenib correlated with CXCR4 levels in gastric cancer cells, and CXCR4 further reduced the transcriptional activity of Wnt/β-Catenin pathway." (PMID 28489887, 2017). "Our analysis of 120 tissue samples from gastric cancer patients showed that increased B7-H3 expression correlated positively with both tumor infiltration depth and CXCR4 expression." (PMID 29069741, 2017). "Up-regulation of TNF-α has the capacity to increase the chemokine receptor CXCR4 levels, which promotes the invasiveness of gastric cancer cells." (PMID 27356745, 2016). "First, we examined CXCR4 expression on a well-known gastric cancer cell line, AGS, and found that, although CXCR4 expression is slightly low on the cells surface of AGS, its intracellular level is significantly high." (PMID 24659999, 2014). "Herein, we examined the expression of CXCR4 in gastric tissues from patients with gastric cancer and found that CXCR4 is expressed in cytoplasm and nucleus of most of the gastric primary tumors." (PMID 24659999, 2014). "More importantly, we are demonstrating for the first time that CXCR4 is expressed in the nucleus of primary gastric cancer." (PMID 24659999, 2014).
gastric cancer (continued). "The in vivo and in vitro studies have identified that CXCR4 was expressed in gastric carcinoma and gastric cancer cell lines, and correlated with the late developmental stages of lymph node cancer." (PMID 24765141, 2014). "In contrast, CXCR4 expression has been shown to be overexpressed in over 23 human cancers including breast, ovarian, melanoma, prostate, and gastric cancers." (PMID 24659999, 2014). "In conclusion, we present evidence for the first time that both cytoplasmic and nuclear expression of CXCR4 are detectable in gastric cancer tissues." (PMID 24659999, 2014). "Stromal cell-derived factor-1 (SDF-1) (CXC chemokine ligand-12)/CXC chemokine receptor 4 (CXCR4) is involved in the carcinogenesis of human gastric cancer, where it stimulates angiogenesis and favors metastasis of tumor cells to distant organs." (PMID 24929539, 2014). "In conclusion, we have found that CXCR4 is expressed in both cytoplasm and nucleus of gastric cancer cells and patients with nuclear CXCR4 expression have a better overall survival." (PMID 24659999, 2014). "Similar to many other cancers which express a high level of CXCR4, gastric cancers are also shown to express a high amount of CXCR4 which is correlated with tumor behaviors such as deep invasion to lymph nodes, liver metastasis, and poor differentiation." (PMID 24659999, 2014). "This identified that the higher concentrations of cyclopamine (50 and 100 μM) markedly downregulated the gene expression of Gli1 and CXCR4 in the gastric cancer cells." (PMID 24765141, 2014). "In the current study, we aimed to study CXCR4 expression in primary gastric cancers and attempted to correlate clinicopathological factors with the pattern of CXCR4 expression." (PMID 24659999, 2014). "First, we used human atrophic gastritis samples as control for gastric cancer and stained them for CXCR4 expression and found that CXCR4 is expressed at a very low level in atrophic gastritis samples." (PMID 24659999, 2014). "In the current study, we found that CXCR4 is expressed in cytoplasm of primary gastric cancer confirming the previous reports." (PMID 24659999, 2014). "To date, the significance of CXCR4 as a potential predictive marker for chemotherapy in gastric cancer has been reported only in cellular models." (PMID 24981311, 2014). "The results were consistent with the gene expression results, as higher concentrations of cyclopamine (50 and 100 μM) downregulated the protein expression of Gli1 and CXCR4 in the gastric cancer cells." (PMID 24765141, 2014). "In agreement with our data, another study previously reported that CXCR4 is expressed in cytoplasm of other gastric cancer cell lines." (PMID 24659999, 2014). "Herein, we studied the expression of CXCR4 in gastric samples from patients with gastric adenocarcinoma as well as human gastric carcinoma cell line, AGS, by employing RT-PCR, immunohistochemistry, and flow cytometry techniques." (PMID 24659999, 2014). "By contrast, down-regulation of CXCR4 diminished the invasion of gastric cancer cells, which was induced by over-expressed RhoE." (PMID 24312338, 2013). "Our studies were designed to investigate the expression and prognostic significance of CXCR4 in patients with gastric cancer." (PMID 23936528, 2013). "PCR array and subsequent transwell assay showed that the regulation of gastric cancer metastasis by RhoE was partially mediated by CXCR4." (PMID 24312338, 2013). "Previous studies had been demonstrated that CXCL12/CXCR4 axis plays an important role in metastasis of many malignancies, including gastric cancer." (PMID 23936528, 2013). "On the basis of TNM stage, detection of CXCR4 expression will be helpful for predicting prognosis for patients with gastric cancer." (PMID 23936528, 2013).